ENSG00000264324 (novel protein)
Gene: Protein-coding gene on chromosome 2 (74,211,604 to 74,363,377, reverse strand). Ensembl gene ENSG00000264324.
Genetic constraint (gnomAD): Missense variants: 248 observed, 249.98 expected, observed/expected ratio (o/e) 0.99, 90% interval 0.89 to 1.1. Synonymous variants: 113 observed, 104.94 expected, observed/expected ratio (o/e) 1.08, 90% interval 0.92 to 1.26.